RFC1 (replication factor C subunit 1)
Diseases named in the same sentence as RFC1 in open-access papers (continued):
Sharing a sentence is not in itself a finding about the gene and the disease.
ischemia (1 paper, 2023). A hypoperfusion of the BLOOD through an organ or tissue caused by a PATHOLOGIC CONSTRICTION or obstruction of its BLOOD VESSELS, or an absence of BLOOD CIRCULATION. "Following ischemia, the expression of RFC1 protein was enhanced significantly compared to controls detected by Western blotting (p = 0.025) and RFC1 immunopositivity (p < 0.0001)." (PMID 37328777, 2023). "In line with that, further augmentation of RFC1 expression by LV-RFC1 intervention before ischemia salvaged the decreased occludin and collagen-4 levels, otherwise which would be attenuated by ischemia." (PMID 37328777, 2023). "A previous gene profiling study showed RFC1 mRNA upregulation following 1 h ischemia / 24 h recanalization induced by high intraocular pressure retinal ischemia model in rats." (PMID 37328777, 2023). "Also, knocking down RFC1 prior to ischemia impaired barrier functions which were demonstrated by endogenous IgG leakage, supporting our findings that RFC1 is essential for the protection of inner BRB during retinal ischemia." (PMID 37328777, 2023). "Besides, the pre-ischemic overexpression of RFC1 partially rescued collagen-4 and occludin levels which would be decreased after ischemia." (PMID 37328777, 2023). "The upregulation of RFC1 may be attempted for diseases other than ischemia where the impairment of BRB or BBB is involved in the pathophysiology." (PMID 37328777, 2023). "Alternatively, the increase of metabolic needs due to acute phase of ischemia might necessitate the upregulation of RFC1 after 1 h of retinal ischemia for the preservation of the barrier properties." (PMID 37328777, 2023). "Overall, NRF-1 may play a complex role in regulating RFC1 in ischemia." (PMID 37328777, 2023). "However, the role of RFC1 neither in the microvasculature nor in ischemia has been clarified." (PMID 37328777, 2023).
medulloblastoma (1 paper, 2015). A malignant, invasive embryonal neoplasm arising from the cerebellum. "The Daoy medulloblastoma cells showed higher relative expression of the RFC1, DHFR and TYMS genes, whereas the expression of these genes was very weak in the MBL-02 medulloblastoma cells." (PMID 25739012, 2015).
monoclonal gammopathy (1 paper, 2025). A condition characterized by the abnormal presence of monoclonal immunoglobulins in the blood or urine. "None of the RFC1 patients had abnormal thyroid function tests, low vitamin B12 or monoclonal gammopathy." (PMID 41322202, 2025).
progressive ataxia (1 paper, 2021).
retinal ischemia (1 paper, 2023). A ischemic disease that involves the retina. "Another study showed that 45 min retinal ischemia followed by 48 h recanalization upregulated RFC1 mRNA in rats." (PMID 37328777, 2023). "When RFC1-siRNA was administered 24 h before retinal ischemia, a significant amount of endogenous IgG extravasation was determined (red arrows)." (PMID 37328777, 2023). "We induced 1 h retinal ischemia by an established method in our laboratory, and observed an increase in RFC1 protein." (PMID 37328777, 2023). "After observing the potential role of RFC1 protein in maintaining the inner BRB, we investigated whether RFC1 protein has a role in retinal ischemia." (PMID 37328777, 2023). "By using these tools, we tried to elucidate the role of RFC1 in the abrupt regulation of inner BRB during physiological conditions and acute retinal ischemia and highlighted its potential role for preserving BRB integrity." (PMID 37328777, 2023). "We also showed that RFC1 is an essential component for maintaining the inner BRB and has fundamental roles in retinal ischemia." (PMID 37328777, 2023). "In contrast, the same study observed no significant change in RFC1 mRNA in 1 h permanent retinal ischemia." (PMID 37328777, 2023). "As scrambled-siRNA administration 24 h before retinal ischemia led to no apparent IgG extravasation, this indicated that decreased RFC1 levels accelerated the inner BRB disruption in acute retinal ischemia." (PMID 37328777, 2023).
rheumatoid arthritis (1 paper, 2015). A chronic, systemic autoimmune disorder characterized by inflammation in the synovial membranes and articular surfaces. "One study found that the RFC-1 -43C>T polymorphism is associated with RFC-1 expression in rheumatoid arthritis patients receiving methotrexate treatment." (PMID 25659099, 2015).
sarcoma (1 paper, 2022). A usually aggressive malignant neoplasm of the soft tissue or bone. "We investigated the prognostic analysis of RFC1-5 in sarcoma using the plotter tool in the GEPIA and Kaplan Meier databases (Kaplan Meier plotter)." (PMID 35483337, 2022). "The mRNA transcription level of RFCs showed a significant difference between normal and sarcoma patients, except RFC1." (PMID 35483337, 2022). "Interestingly, in these two databases, poor overall survival (OS) and disease-free survival (DFS) of sarcoma were related to the upregulation of RFC1, but with meaningless." (PMID 35483337, 2022). "The results showed that RFC2, RFC4, and RFC5 were upregulated in sarcoma patients, while the high expression levels of RFC1 and RFC3 were both with no significance." (PMID 35483337, 2022). "In addition, Cancer Cell Line Encyclopedia (CCLE) dataset analysis indicated that RFC1, RFC2, RFC3, RFC4, and RFC5 were elevated expressed in sarcoma cell lines." (PMID 35483337, 2022). "Unlike other subunits, RFC1 is rarely reported to have a relationship with sarcoma." (PMID 35483337, 2022).
sleep disorder (1 paper, 2025). A change from the patient's baseline sleeping pattern, in the hours slept and/or an alteration/dysfunction in the stages of sleep. "RFC1‐spectrum disorders are associated with a high prevalence of sleep disorders and impaired QoL, highlighting the need for screening." (PMID 40879541, 2025). "This study aimed to investigate the prevalence and characteristics of sleep disorders in patients with RFC1‐spectrum disorders and their impact on quality of life (QoL)." (PMID 40879541, 2025). "RFC1‐related disease is characterized by a high prevalence of sleep disorders and poor QoL, which constitute a significant component of the disease's non‐motor spectrum." (PMID 40879541, 2025). "This study aimed to evaluate the prevalence of sleep disorders in patients with RFC1‐spectrum disorders and to assess their impact on quality of life (QoL)." (PMID 40879541, 2025).
spastic ataxia (1 paper, 2019). "WGS of the four RFC1-negative CANVAS-affected families identified plausible variants in three, with genomic re-diagnosis of SCA3, spastic ataxia of the Charlevoix-Saguenay type, and SCA45." (PMID 31230722, 2019).
Spinocerebellar atrophy (1 paper, 2024). Atrophy affecting the cerebellum and the spinocerebellar tracts of the spinal cord. "We identified biallelic RFC1 ACAGG expansions of 1000 ~ repeats in three affected siblings having sensorimotor neuronopathy with spinocerebellar atrophy initially presenting with painful muscle cramps and paroxysmal dry cough." (PMID 38324175, 2024). "In this study, we identified biallelic ACAGG expansions in RFC1 in a Japanese pedigree who had sensorimotor neuronopathy with spinocerebellar atrophy, initially manifesting painful muscle cramps and paroxysmal dry cough and later developing diffuse amyotrophy." (PMID 38324175, 2024).
thyroid cancer (1 paper, 2023). "Furthermore, RFC1 80A > G was also associated with thyroid cancer, but only under the recessive model, whereas MTR 2756A > G showed an association with tumor size and aggressive behavior." (PMID 37189693, 2023).
triple-negative breast carcinoma (1 paper, 2023). An invasive breast carcinoma which is negative for expression of estrogen receptor (ER), progesterone receptor (PR), and human epidermal growth factor receptor 2 (HER2). "Another NER pathway gene was seen to be induced by PAC only in triple-negative breast cancer, termed replication factor C subunit 1 (RFC1)." (PMID 37298600, 2023).
cancer (16 papers, 2012 to 2025). A tumor composed of atypical neoplastic, often pleomorphic cells that invade other tissues. "As the repeat-hosting gene RFC1 encodes for the largest subunit of the replication factor complex, essential to DNA replication and repair, detailed data concerning cancer history were also collected." (PMID 32040566, 2020). "The relationship among the RFC1 80G>A polymorphism, cancer risk and clinical outcome have been the objects of several studies, though with contrasting reports." (PMID 27936032, 2016). "A meta-analysis on the association between cancer risk and the RFC1 G80A polymorphism was carried out by Huang S. The findings demonstrated a strong correlation, especially in some ethnic groups, between the RFC1 G80A polymorphism and the incidence of solid cancer." (PMID 40270992, 2025). "Evidence indicates RFC1 G80A polymorphism as a risk factor for a number of cancers." (PMID 27222703, 2016). "Although the precise functions of RFC1 in cancer are still unknown, our findings suggest that the small-molecule single target, CHEMBL430483, and multiple target molecules could be potential treatments for CRC." (PMID 38504096, 2024). "Unlike high-affinity FRs that accumulate folates through endocytosis folate transport systems, including RFC1 and PCFT have recently attracted attention for their ability to deliver antifolate drugs to cancer cells." (PMID 34169173, 2021). "Genotyping for BHMT 716A>G, DHFR 19bp ins/del, MTHFD1 1958G>A, MTHFR 677C>T, MTR 2756A>G, MTRR 66A>G, RFC1 80G>A, SHMT1 1420C>T, TCII 776C>G and TS 2rpt-3rpt was performed in 102 cancer patients and 363 cancer-free subjects." (PMID 28968444, 2017). "No RFC1-positive patients had a history of cancer or had a history of heavy alcohol use." (PMID 41322202, 2025).
tumor (15 papers, 2011 to 2025). "Furthermore, the results indicate that higher tumoral expression of RFC‐1 is associated with improved tumor response to FLV‐based chemotherapy, consistent with previous reports on patients with stage III CRC." (PMID 40357991, 2025). "The percentage of tumor epithelial cells in specimens correlated positively with RFC‐1 expression and with ABCC3 expression in group 1, indicating that these genes are either epithelial‐specific or not highly expressed in stromal cells." (PMID 40357991, 2025). "In group 1, high RFC‐1 and low TYMS expression were associated with better tumor response (p = 0.014 and p = 0.032, respectively)." (PMID 40357991, 2025). "In the future, the tumor-suppressive role of miR-26a-5p targeted RFC1 and miR-636 targeted RFC5 in CRC progression needs to be further investigated in a larger cohort of patients." (PMID 38504096, 2024). "The multivariable analysis further underscored the significance of age, ABCC3, ERCC1, RFC1, and specific tumour histologies in predicting treatment outcomes." (PMID 39335211, 2024). "The results showed that RFC1-5 were all positively correlated with tumor purity, negatively correlated with the infiltration of CD4+ T cell and macrophage, with significance." (PMID 35483337, 2022). "After LV injection, the expression of FPGS, GGH, MTHFD1L, and SLC19A1/RFC-1 was significantly higher in tumour tissue compared to the mucosa." (PMID 30269276, 2018). "Tumor RhoA scores increased with decitabine (P = 0.03), and RFC1 also increased in patients with pre-decitabine scores ≤150 (P = 0.004)." (PMID 24401732, 2014). "Conversely, there was a trend towards tumor RFC1 scores being lower in patients with last prior therapy >3 months versus ≤3 months earlier (42.5 versus 135, P = 0.06)." (PMID 24401732, 2014). "Compared to other tumor types, adenocarcinomas had higher pre-decitabine IHC scores for reduced folate carrier (RFC1) (median score 240 in adenocarcinomas versus 80 in others, P = 0.0096)." (PMID 24401732, 2014). "Additionally, increasing doses of LV influence folate‐related gene expression, and there seems to be a correlation between the expression of the genes ABCC3, PCFT, and RFC‐1 and folate concentrations in tumor tissue." (PMID 40357991, 2025). "Additionally, synthetic folate analogs such as pralatrexate have anti-tumor effects and play a role in tumor reduced folate carrier (RFC-1) gene expression." (PMID 34204115, 2021). "A higher incidence of neoplasm might have been expected as the result of RFC1 dysfunction together with impaired DNA damage response." (PMID 32040566, 2020). "Since OAT2 and RFC1 are the major transporters of 5-FU and LV, respectively, the expression levels of OAT2 and RFC1 may be candidate biomarkers for the prediction of tumor response to UFT/LV chemotherapy." (PMID 24649225, 2013). "ABCC3, RFC‐1, PCFT, MFT, MTHFD2, and TYMS expression was determined by qPCR and related to tumor response and 3‐year progression‐free survival (PFS)." (PMID 40357991, 2025). "Our study revealed that RFC1 and RFC5 are two significant antitumor mRNA and inhibitors of tumor progression." (PMID 38504096, 2024). "The RFC family consists of five protein subunits, RFC1, RFC2, RFC3, RFC4, and RFC512; which are strongly connected with tumor growth and metastasis." (PMID 38504096, 2024). "RFC1 and PCFT are functionally distinct in that RFC1 is optimal at neutral pH (~7.4) and is known as the main route of transport of most antifolates into tumour cells." (PMID 34169173, 2021). "After LV injection, a significantly higher gene expression level of GGH, MTHFD1L, SLC19A1/RFC-1, and FPGS was seen in tumour tissue compared to mucosa." (PMID 30269276, 2018). "The results of the study showed that tumour tissue of untreated patients had higher expression of FPGS, GGH, MTHFD1L, and SLC19A1/RFC-1 compared with mucosa, whereas expression of ABCC3/MRP3 and SLC46A1/PCFT was higher in mucosa compared with tumour." (PMID 30269276, 2018).
tumor (continued). "Pralatrexate is a dihydrofolate reductase (DHFR) inhibitor with high affinity for reduced folate carrier 1 (RFC-1) and folylpolyglutamate synthetase (FPGS), resulting in extensive internalization and accumulation in tumour cells." (PMID 21179031, 2011). "Pralatrexate is an antifolate with high affinity for the reduced folate carrier 1 (RFC-1) protein and folylpolyglutamate synthetase (FPGS), resulting in extensive internalization and accumulation within tumour cells." (PMID 21179031, 2011). "The aim of the present study was to assess the association between primary tumor expression of six selected folate pathway genes, ABCC3, RFC‐1, PCFT, MFT, MTHFD2, and TYMS, and tumor response as well as 3‐year progression‐free survival (PFS) of patients with mCRC." (PMID 40357991, 2025). "This is in contrast to the clear but non-significant upregulation in ERCC1 (p = 0.080) and RFC1 (p = 0.075) between the tumours and normal muscle tissue of the COS patients." (PMID 39335211, 2024). "As an interesting observation, RFC1 was recently determined as a cGAMP importer in the cyclic GMP–AMP synthase (cGAS)–stimulator of interferon genes (STING) pathway that has a role in inflammation, cellular stress, and tumor angiogenesis." (PMID 37328777, 2023). "These genes, such as RFC1, XPO4, THEGL, SLC19A3, TBC1D4, and KCNH5, may have specific functions in metastatic tumour cells." (PMID 34507604, 2021). "However, RFC1 expression was not confirmed as an independent predictive factor for tumor response to treatment." (PMID 24649225, 2013). "However, the expression levels of RFC1, RFC2, RFC3, and RFC4 did not exhibit significant differences in various tumor stages." (PMID 38504096, 2024).
neurological diseases (7 papers, 2021 to 2025). "Of particular interest here was a high fraction of cases with long expansions in the FGF14 STR region, which was only recently characterized as a common cause of neurological disorder partially overlapping RFC1-related phenotypes." (PMID 40141365, 2025). "Within this study, we identified biallelic pathogenic RFC1 expansions in 15.3% of our cohort of 242 Australasian, neurological disease patients." (PMID 37621409, 2023). "Our results show that RFC1 pathogenic expansions make a substantial contribution to neurological disease in the Australasian population and further extend the heterogeneity of the locus." (PMID 37621409, 2023). "For example, expansions in replication factor C subunit 1 (RFC1) and frataxin (FXN) are also associated with neurologic disorders." (PMID 41278766, 2025). "Therefore, this method enables all patient samples tested using Version 6 of the PathWest neurological disease gene panel to be pre-screened for biallelic RFC1 expansions." (PMID 37621409, 2023). "Here, we also show that short-read sequencing can be used to reliably screen for the presence or absence of biallelic RFC1 expansions in all samples tested using the PathWest targeted neurological disease gene panel." (PMID 37621409, 2023).
neurodegenerative disease (4 papers, 2021 to 2024). A disorder of the central nervous system characterized by gradual and progressive loss of neural tissue and neurologic function. "Our results for the first time report the G4 structure as a fundamental determinant for the pathogenic RFC1 AAGGG repeats linked to gene dysregulation, providing a possible molecular mechanism for the pathogenesis of relevant neurodegenerative diseases." (PMID 38266156, 2024). "Non-coding repeat expansions within RFC1 and NOTCH2NLC genes have lately been linked to multisystem neurodegenerative diseases, which also shed light on yet undiagnosed patients with inherited peripheral neuropathies." (PMID 36061987, 2022).
genetic disorder (3 papers, 2021 to 2026). "A RFC1 repeat expansion was positive only in proband and revealed a homozygous expansion confirming the co-existence of two Mendelian genetic disorders." (PMID 39544699, 2024). "The genetic disorder was discovered in 2019, under the form of abnormal biallelic expansion in the replication factor C subunit 1 (RFC1) in a population of late-onset ataxia." (PMID 33011895, 2021).
adenocarcinoma (1 paper, 2014). A common cancer characterized by the presence of malignant glandular cells. "The changes in median IHC scores with decitabine were 30 (adenocarcinomas) versus 20 (others) for RhoA (P = 0.63), 30 (adenocarcinomas) versus 12 (others) for RFC1, -5 (adenocarcinomas) versus 0 (others) for FOLR1 (P = 0.89) and 0 (adenocarcinomas) versus 0 (others) for GLUT4 (P = 0.96)." (PMID 24401732, 2014).
brain disorder (1 paper, 2023). A disease affecting the brain or part of the brain. "So, our study offers a recognition for the roles of RFC1 protein in the CNS and deepens our understanding of other critical functions as well as novel treatment strategies for brain disorders." (PMID 37328777, 2023).
infection (1 paper, 2009). The state of being infected such as from the introduction of a foreign agent such as serum, vaccine, antigenic substance or organism. "Another relevant gene, RFC1 (replication factor 1), had higher transcript levels in bone marrow-derived macrophages (BMDM) isolated from disease susceptible BALB/c mice than from resistant C57BL/6 mice post infection with Yersinia enterocolitica." (PMID 19432955, 2009).